ACAN (aggrecan)
Diseases named in the same sentence as ACAN in open-access papers (continued):
Sharing a sentence is not in itself a finding about the gene and the disease.
bipolar disorder (5 papers, 2014 to 2022). A disorder of the brain that causes unusual shifts in mood, energy, activity levels and the ability to carry out day-to-day tasks. "However, chronic lithium treatment correlated with higher numbers of aggrecan and chondroitin 6‐sulphated PNNs in subjects with bipolar disorder in our previous human postmortem studies, suggesting that lithium may maintain or protect PNNs." (PMID 33070392, 2021).
breast carcinoma (5 papers, 2014 to 2023). "However, thus far, the only documented substrates for ADAMTS-15 are VCAN and aggrecan, while in breast cancer, where the effects of ADAMTS-15 on cell migration were shown to involve syndecan-4, this was independent of its metalloproteinase activity." (PMID 32354091, 2020). "Lastly, associations between SNPs in ACAN/BGN/DCN genes and treatment characteristics may have an undetermined influence on our findings and should be explored in greater depth with breast cancer risk." (PMID 34162438, 2021).
ischemia (5 papers, 2017 to 2022). A hypoperfusion of the BLOOD through an organ or tissue caused by a PATHOLOGIC CONSTRICTION or obstruction of its BLOOD VESSELS, or an absence of BLOOD CIRCULATION. "Fibronectin was significantly elevated in the retina following ischemia, while laminin, tenascin-C and aggrecan showed enhanced immunoreactivity in the optic nerve after ischemia, indicating their regulatory role during neurodegeneration." (PMID 35269741, 2022). "Therefore, we speculated that ischemia of the lumbar spine produced by lumbar artery ligation would stimulate the synthesis of aggrecan, particularly in the NP of corresponding IVDs." (PMID 31351455, 2019). "Our histological observations of the rabbit NP suggest that matrix metabolism synthesis, especially aggrecan, would be stimulated in the PCM in response to ischemia in corresponding IVDs." (PMID 31351455, 2019).
myopia (5 papers, 2010 to 2024). "The results showed that ACAN rs3784757 and rs1516794 T minor allele were significantly associated with high myopia as a potential protective factor with an odds ratio of 0.83 (95%CI 0.70–0.99) and 0.79 (95%CI 0.64–0.97), respectively." (PMID 39597899, 2024). "In myopia, the posterior sclera remodeling was characterized by physical loss of the scleral extracellular matrix which were mainly due to the reduced production and increased degradation of type I collagen and aggrecan." (PMID 21403850, 2011). "Moreover, in the recessive model, rs38857 and rs10215153 in the MET gene and rs3784757 in the ACAN gene were significantly associated with high myopia and showed odds ratios of 4.14 (95%CI 1.38–12.43), 5.74 (95%CI 1.27–25.95) and 0.52 (95%CI 0.28–0.97), respectively." (PMID 39597899, 2024). "In addition, one patient with a mildly advanced bone age was found to harbor a frameshift mutation of the ACAN gene; whereas, one patient with early-onset myopia, cleft palate, flat nose, and short fingers was found to have a hemizygous mutation of the COL2A1 gene." (PMID 30541462, 2018). "Interactions between fibulin-1 and aggrecan may be important, and the modulation of aggrecan levels and distribution could play a key role in changing the scleral creep rate, which is associated with axial elongation of the eye and the development of myopia." (PMID 20405022, 2010). "Further research on the function of fibulin-1 and its interaction with aggrecan in sclera during the development of myopia is warranted." (PMID 20405022, 2010).
atherosclerosis (4 papers, 2018 to 2023). A disease characterized by the build-up of fatty material and calcium deposition in the arterial wall resulting in partial or complete occlusion of the arterial lumen. "The proteomics data also revealed sex differences in atherosclerosis, with large-aggregating proteoglycans versican and aggrecan being more abundant in females and exhibiting an inverse correlation with estradiol levels." (PMID 37646165, 2023). "Aggrecan has been associated with cardiovascular disease, with increased or decreased aggrecan reported in aortic aneurysms, atherosclerosis, venous hypertension, and cardiac valve anomalies." (PMID 34681829, 2021). "Inactivation of ADAMTS1 by HOCl, if this occurs in vivo, may result in a disturbance in aggrecan homeostasis, and accumulation during the development of atherosclerosis." (PMID 36829979, 2023).
chondrosarcoma (4 papers, 2012 to 2021). A malignant cartilaginous matrix-producing mesenchymal neoplasm arising from the bone and soft tissue. "Since hypoxia is strongly evident in chondrosarcoma, upregulated aggrecan expression is suggested to be a protective factor for chondrosarcoma cell survival." (PMID 34069554, 2021). "The most detailed studied biosynthesis of cartilage PGs is that of aggrecan and the results are coming from cell and tissue cultures, as well as from Swarm rat chondrosarcoma." (PMID 25105124, 2014). "In chondrosarcoma, the cells are continuing to synthesize aggrecan; however, in other types of cancer in cartilaginous tissues, aggrecan core protein expression is highly decreased, possibly due to the depletion of chondrocytes." (PMID 25105124, 2014). "Interestingly, aggrecan expression increases when human chondrosarcoma HCS-2/8 cells are cultured during extended periods in a 5% low-oxygen atmosphere." (PMID 34069554, 2021).
chordoma (4 papers, 2010 to 2025). Chordomas are rare malignant tumors arising from embryonic remnants of the notochord in axial skeleton. "Although only described in the context of glycosylation, we hypothesize that ALG11 could be involved in biosynthesis of glucosaminoglycans/aggrecan that represent a key component of the extracellular matrix of chorda dorsalis, nucleosus pulposus, and classical chordoma." (PMID 24503940, 2014). "However, it has also been suggested that notochordal cells could differentiate into the adult disc nucleus cell phenotype since chordomas, which arise from embryonic notochordal remnants, show chondrogenic potential and can differentiate into cartilage-type cells expressing collagen II and aggrecan." (PMID 20152014, 2010). "ACAN, CA12, and RAB3B were differentially expressed in chordoma versus normal tissue and mesenchymal tumors but not IVD." (PMID 21253487, 2010).
Marfan syndrome (4 papers, 2021 to 2022). A disorder of the connective tissue. "Animal models of Marfan syndrome with mutations that reduce the amount of fibrillin-1 produced to display a reduction in cleaved aggrecan compared with wild-type mice." (PMID 36012466, 2022). "Aggrecan, in particular, was found to be accumulated in a mouse model of severe Marfan syndrome." (PMID 35743192, 2022). "Aggrecan is a hyalectan that confers viscoelasticity and load-bearing properties to tissues in which it is expressed, and its accumulation has been described in myxomatous valves of a murine model of Marfan syndrome." (PMID 33669101, 2021).
Obesity (4 papers, 2010 to 2022). Accumulation of substantial excess body fat. "The RT-PCR analysis showed major changes between both groups with an elevated mRNA level of growth factors, aggrecan and TIMP-2 in chondrocytes from obese patients suggesting that the chondrocyte metabolic activity is increased with obesity." (PMID 20534145, 2010).
ankylosing spondylitis (3 papers, 2006 to 2015). An autoimmune chronic inflammatory disorder characterized by inflammation in the vertebral joints of the spine and sacroiliac joints. "While the pathogenic cause of ankylosing spondylitis remains unclear, previous studies have revealed a T cell response to aggrecan, which provides valuable information on the disease pathogenesis." (PMID 25452811, 2015). "Previous studies show that the proteoglycan aggrecan is a target for autoreactive T cells in RA and ankylosing spondylitis." (PMID 17129378, 2006). "Furthermore, T cell have been found to respond to aggrecan in ankylosing spondylitis, indicating that T cells plays a key role in the pathogenesis of ankylosing spondylitis." (PMID 25452811, 2015).
Autoimmunity (3 papers, 2012 to 2016). The occurrence of an immune reaction against the organism's own cells or tissues. "Although autoimmunity to cartilage proteoglycans has been studied less intensively than autoimmunity to type II collagen, cartilage PG (aggrecan) is considered as causal/contributing factor in rheumatoid joint disease." (PMID 24605340, 2014). "We recently described a previously unreported uveitis in a murine model of spondyloarthropathy triggered by autoimmunity to aggrecan, a prominent proteoglycan (PG) macromolecule in cartilage." (PMID 22269151, 2012). "All these studies suggest that cartilage PG aggrecan may play an important role in the development of autoimmunity against peripheral joints." (PMID 24605340, 2014).
gastric cancer (3 papers, 2015 to 2024). A primary or metastatic malignant neoplasm involving the stomach. "In previous study, ACAN was selected as a candidate biomarker for targeted therapy against gastric cancer." (PMID 39392257, 2024). "The stage-based assessment of overexpressed genes showed significant upregulation of CST1, INHBA, ACAN, HSP90AB1, and HSPD1 genes across all stages, including early, locally advanced and metastatic stomach cancer." (PMID 33828156, 2021). "Our analysis showed that compared with normal stomach tissue, CST1, INHBA, ACAN, HSP90AB1, and HSPD1 were the leading five genes that were overexpressed in stomach cancer." (PMID 33828156, 2021). "Comparison between normal stomach tissue and stomach tumors showed that CST1 (p = 3.97E−21), INHBA (p = 9.22E−20), ACAN (p = 1.08E−19), HSP90AB1 (p = 2.62E−19), and HSPD1 (p = 3.91E−19) were the leading five genes that were overexpressed in stomach cancer." (PMID 33828156, 2021).
hepatocellular carcinoma (3 papers, 2016 to 2021). A malignant tumor that arises from hepatocytes. "Six genes carrying DNVs were associated with human developmental disorders involving epithelial, connective or bone morphologies (PXDN, RTEL1, ANKRD11, MAP2K1, CYLD, ACAN) and four linked with cholangio- and hepatocellular carcinomas (PIK3CA, TLN1 CYLD, MAP2K1)." (PMID 27955658, 2016). "Specific extracellular matrix proteoglycans, such as versican, aggrecan, biglycan, and decorin, which are increased in rat hepatocellular carcinomas, may affect binding with the C4S attachments on the proteoglycan." (PMID 27078017, 2016). "Serum/glucocorticoid regulated kinase family member 3 (SGK3), a member of Aggrecan (AGC) protein kinase family member, acts as an oncogene in human cancers such as osteosarcoma (OS), hepatocellular carcinoma (HCC) and breast cancer." (PMID 34740363, 2021).
Hernia (3 papers, 2020 to 2023). "Using the Pig QTL database, two DE genes in both groups of hernias studied here were located in QTL regions already identified as being associated to SH hernia in pigs: the ACAN and BCHE genes were mapped, respectively, in the QTLs 55892 (SSC7) and 8794 (SSC13)." (PMID 33513662, 2021). "Polymorphisms in the ACAN have already been associated with hernias and cartilage degeneration." (PMID 32379844, 2020). "Among the DE genes in the two types of hernia, ACAN and BCHE (Butyrylcholinesterase) are highlight since they have already been located in QTL regions associated to scrotal/inguinal hernia." (PMID 33513662, 2021). "The ACAN gene was upregulated in animals affected with hernia, which is in accordance with the histopathological analyses that evidenced a larger amount of collagen compared to normal pigs." (PMID 33513662, 2021). "The ACAN gene belongs to the aggrecan proteoglycan family and was 2.8 times more expressed in the hernia-affected animals than in the normal pigs." (PMID 32379844, 2020). "Moreover, ACAN upregulation in animals affected with hernia can generate an exaggerated collagen production, which has already been related to hernia previously." (PMID 33513662, 2021). "Quantitative real-time PCR was performed for MMP13, VIT, ACAN, and COL6A5 in muscle and connective tissue for all 68 animals, revealing differences in the mRNA level of MMP13 and VIT between the control and hernia pigs." (PMID 37895252, 2023). "The results pointed out ACAN, MMPs, COLs, EPYC, VIT, CCBE1 and LGALS3 genes as strong candidates to trigger umbilical hernias in pigs, because they are involved in hernia related biological processes since the embryogenesis." (PMID 32379844, 2020). "Subsequently, the post hoc test showed significantly lower transcript levels (padj. < 0.05) in group G4 than in groups G1, G2, and G3, indicating that the altered ACAN expression was not related with the presence of hernia." (PMID 37895252, 2023). "The microtubule associated protein 1 light chain 3 γ (MAP1LC3C), vitrin (VIT), aggrecan (ACAN), alkaline ceramidase 2 (ACER2), potassium calcium-activated channel subfamily M α 1 (KCNMA1) and synaptopodin 2 (SYNPO2) genes are highlighted as candidates to trigger both types of hernia." (PMID 33513662, 2021).
Inguinal hernia (3 papers, 2020 to 2023). Protrusion of the contents of the abdominal cavity through the inguinal canal. "The localization of ACAN in the QTL region for scrotal/inguinal hernias suggests a pleiotropic effect of this gene, being also involved in the manifestation of umbilical hernia." (PMID 32379844, 2020). "In the case of inguinal hernia, only the ACAN gene showed decreased mRNA levels in the muscle tissue of the inguinal canal in older animals, which may be a consequence of aging rather than pathological status." (PMID 37895252, 2023). "Moreover, three other DE genes found in our study were located in QTL regions for scrotal/inguinal hernias: ACAN mapped in SSC7, Butyrylcholinesterase (BCHE) in SSC13 and KANK3 in SSC2." (PMID 32379844, 2020).
intervertebral disc disorders (3 papers, 2017 to 2022). "The lower number of frequent repetitions in the VNTR aggrecan gene was associated with a six-time increase of lumbar disc degeneration." (PMID 35919638, 2022). "Significant associations were identified in our previous study between single nucleotide variants (SNVs) of candidate genes of the aggrecan metabolic pathway and lumbar disc degeneration." (PMID 28742099, 2017). "Considering the findings of the previous genetic study on lumbar disc degeneration and current evidence available in the literature, we extended our research to investigate the associations of candidate genes of the aggrecan metabolic pathway with the severity of lumbar disc herniation." (PMID 28742099, 2017). "So, the aim of this study, was to investigate the relation between aggrecan gene VNTR and VDR gene rs731236 (TaqI) polymorphisms and lumbar intervertebral disc degeneration in a population in the North of Iran." (PMID 35919638, 2022).
juvenile idiopathic arthritis (3 papers, 2006 to 2025). Juvenile idiopathic arthritis (JIA) is the term used to describe a group of inflammatory articular disorders of unknown cause that begin before the age of 16 and last over 6 weeks. "Therefore, our study aimed to evaluate the diagnostic utility of plasma proteoglycan profiles, namely, aggrecan, decorin, and biglycan, released from osteoarticular structures into the blood of children with juvenile idiopathic arthritis." (PMID 41465591, 2025). "Although concentrations of aggrecan and decorin have not previously been assessed in the blood of children with juvenile idiopathic arthritis, the concentrations of their degradation products, i.e., aggrecan neoepitopes (ARGS), dermatan sulfates (DS), and keratan sulfates (KS), have been studied." (PMID 41465591, 2025).
melanoma (3 papers, 2015 to 2025). A malignant, usually aggressive tumor composed of atypical, neoplastic melanocytes. "About twice as many A375 and B16-F10 melanoma cells incubated with MMP-13-digested collagen II, III, IV, aggrecan or laminin-5 invaded the transwell membrane as untreated controls." (PMID 25749207, 2015).
status epilepticus (3 papers, 2015 to 2019). Status epilepticus is defined as a continuous seizure lasting more than 30 min, or two or more seizures without full recovery of consciousness between any of them. "The increased digestion suggests aggrecan proteolysis as an early step in PNNs loss (visible here 7 days after stroke and after 5 days of EE), similarly to what has been described after status epilepticus." (PMID 28290150, 2018). "Status epilepticus is associated with reduced PN-stabilizing components and aggrecan expression." (PMID 26135580, 2015).
amyotrophic lateral sclerosis (2 papers, 2023 to 2025). Amyotrophic lateral sclerosis (ALS) is a neurodegenerative disease characterized by progressive muscular paralysis reflecting degeneration of motor neurons in the primary motor cortex, corticospinal tracts, brainstem and spinal cord. "Similarly, in mouse models of Amyotrophic Lateral Sclerosis (ALS), activated microglia and astrocytes in the ventral horn show increased engulfment of the core PNN protein aggrecan, coinciding with the timing of PNN breakdown around vulnerable motor neurons." (PMID 40728680, 2025).
aneurysm (2 papers, 2021 to 2023). Bulging or ballooning in an area of an artery secondary to arterial wall weakening. "Analyzing the ACAN levels in patients with cardiac complications (STEMI or aneurysms) showed a specificity of more than 80%." (PMID 33990642, 2021). "In the in vivo study, we detected a gross lower expression level of CD68 and ARG1 (macrophage), Aggrecan (chondrocyte), OPN (osteoblast), ADIPQ (adipocytes), CD34 (mesenchymal cells), and LUM (fibroblasts) in the FAM3A-overexpressing aneurysm tissues compared with the matched Ad-sham tissues." (PMID 37660071, 2023).
aneurysmal disease (2 papers, 2018 to 2023). "All these features recapitulate human aneurysmal disease, and the latter, involving massive accrual of aggrecan and other proteoglycans, is considered a defining facet of aortic pathology in humans." (PMID 37561588, 2023).
Cardiomyopathies (2 papers, 2024 to 2025). "These disorders are categorized into major clinical groups, such as Skeletal Dysplasias (e.g., analysis of genes like ACAN, ACP5, and ACVR1), Osteogenesis Imperfecta (COL1A1, COL1A2, BMP1), Metabolic Disorders (ACE, AGT, BICC1), and Cardiomyopathies, among others." (PMID 40282387, 2025).
cartilage disease (2 papers, 2018 to 2022). Softening and degeneration of the CARTILAGE. "Although aggrecan dysfunction is strongly associated with chondropathy and distinct phenotypes, only a few patients with aggrecan deficiency have been reported, likely due to the wide phenotypic spectrum of ACAN mutations." (PMID 29769040, 2018).
diabetes (2 papers, 2014 to 2019). "Furthermore, to assess the influence of diabetes on aggrecan, a major proteoglycan in articular cartilage, the sections were evaluated by safranin o staining." (PMID 31164994, 2019). "Our study showed that PAI-1 deficiency does not accelerate the bone repair process in female mice without diabetes, but it increases the cartilage matrix and the levels of chondrogenic marker mRNA such as type II collagen and aggrecan at the damaged site in female mice without diabetes." (PMID 24651693, 2014).
epilepsy (2 papers, 2016 to 2019). A brain disorder characterized by episodes of abnormally increased neuronal discharge resulting in transient episodes of sensory or motor neurological dysfunction, or psychic dysfunction. "The deficits of PNNs measured by reduced WFA numbers and decreased tenascin-R, aggrecan and neurocan protein levels might be related to the pathophysiology of epilepsy induced by PTZ." (PMID 27880801, 2016).